ZCCHC14 (zinc finger CCHC-type containing 14)
Synonyms: BDG29; MGC14139; BDG-29
Tractability: PROTAC: ubiquitination databases record sites on it.
Gene: Protein-coding gene on chromosome 16 (87,406,246 to 87,493,024, reverse strand). Ensembl gene ENSG00000140948.
Subcellular location (Human Protein Atlas): Nuclear membrane
Gene Ontology:
Molecular function: protein binding; nucleic acid binding; phosphatidylinositol binding; zinc ion binding
Genetic constraint (gnomAD): Loss-of-function variants: 16 observed, 77.6 expected, observed/expected ratio (o/e) 0.21, 90% interval 0.14 to 0.31. The synonymous counts are far from expectation, so gnomAD's model fits this gene poorly and the ratio says little. Missense variants: 1,285 observed, 1,385.1 expected, observed/expected ratio (o/e) 0.93, 90% interval 0.88 to 0.97. Synonymous variants: 769 observed, 611.71 expected, observed/expected ratio (o/e) 1.26, 90% interval 1.18 to 1.33.
Homologues: Orthologues: macaque ZCCHC14 (99% identical), mouse Zcchc14 (88% identical), chimpanzee ZCCHC14 (87% identical), rat Zcchc14 (87% identical), dog ZCCHC14 (84% identical), pig ZCCHC14 (73% identical), rabbit ZCCHC14 (72% identical), guinea pig ZCCHC14 (64% identical), tropical clawed frog zcchc14 (63% identical), zebrafish zcchc14 (42% identical), Drosophila melanogaster CG10492 (14% identical), Caenorhabditis elegans gls-1 (12% identical). Paralogues in human: ZCCHC2 (30% identical).
Diseases named in the same sentence as ZCCHC14 in open-access papers:
ZCCHC14 is named in the same sentence as 18 diseases in open-access papers, as found by Europe PMC text mining. Sharing a sentence is not in itself a finding about the gene and the disease. The quoted sentences say what the papers report.
lung carcinoma (2 papers, 2016 to 2021). "In this research, we explored the expression, function and related molecular mechanisms of ZCCHC14 in human non–small cell lung cancer (NSCLC)." (PMID 33345444, 2021). "To determine whether ZCCHC14 plays a role in lung cancer cells through the P38 signalling pathway, we added the P38 pathway inhibitor doramapimod (BIRB 796)." (PMID 33345444, 2021). "The mechanism of how ZCCHC14 participates in the antagonistic action needs further study and may provide insights into molecular targeted therapies for lung cancer." (PMID 33345444, 2021). "However, the function of ZCCHC14 and its pathogenesis in lung cancer needs to be further analysed." (PMID 33345444, 2021). "ZCCHC14 exerts an antagonistic effect through which function in lung cancer is unknown." (PMID 33345444, 2021). "Immunoblotting analysis showed that ZCCHC14 was expressed in HBE and lung cancer cells and was under expressed to varying degrees in LK2, H460 and H292 cells." (PMID 33345444, 2021). "Firstly, the expression of ZCCHC14 was detected in HBE cells and lung cancer cells A549, H1299, LK2, H460 and H292." (PMID 33345444, 2021). "The ZCCHC14 negative rate was 73% in lung cancer tissues (76/104) and 90% brain metastases tissues (43/48), and both differences were statistically significant (P < .05)." (PMID 33345444, 2021). "In particular, the expression of ZCCHC14 in patients with lung cancer and brain metastasis was different than in patients without brain metastasis, indicating that ZCCHC14 may be more relevant to the former condition." (PMID 33345444, 2021).
nicotine dependence (2 papers, 2015 to 2021). Physical and psychological dependence on nicotine. "The other CpG island that was not differentially methylated in the TCGA tumors is associated with the zinc-finger protein ZCCHC14, which is an intriguing locus, as SNPs in that gene have been associated with nicotine dependence." (PMID 26635906, 2015). "Using meta‐analysis associated with whole genome analysis, researchers determined that the SNP of ZCCHC14 may be caused by susceptibility of nicotine dependence (ND) and a reason for alcohol addiction." (PMID 33345444, 2021).
gastritis (1 paper, 2023). Inflammation of the stomach. "In conclusion, this study found that circRNA_15430 was downregulated in GC tissues and HP + gastritis tissues, suppressed cell proliferation and migration and promoted cell apoptosis, HP infected the associated autophagy by the miR-382-5p/ZCCHC14 axis in GC cells." (PMID 37626393, 2023). "Additionally, miR-382-5p was increased in HP + gastritis tissue and HP-infected MGC-803 cells while ZCCHC14 decreased in HP-infected MGC-803 cells." (PMID 37626393, 2023).
Infertility (1 paper, 2025). "These latter SNPs are located in two genes, Zinc Finger CCHC-Type Containing 14 (ZCCHC14) and Junctophilin 3 (JPH3), neither of which have any previously published connections to infertility." (PMID 41325449, 2025).
lung adenocarcinoma (1 paper, 2022). A carcinoma that arises from the lung and is characterized by the presence of malignant glandular epithelial cells. "Furthermore, cell model revealed that miR-2355-3p inhibited progression of lung adenocarcinoma by targeting zinc finger CCHC-type containing 14 (ZCCHC14), indicating miR-2355-3p might become a potential biomarker for the diagnosis of lung adenocarcinoma." (PMID 35611768, 2022).
small vessel stroke (1 paper, 2021). "In addition, a Genome Wide Association Study (GWAS) indicated that the leading single‐nucleotide polymorphism in small vessel stroke is associated with mRNA expression of ZCCHC14 in arterial tissues, indicating that ZCCHC14 may play a role in cerebrovascular formation and management." (PMID 33345444, 2021).
Stroke (1 paper, 2022). Sudden impairment of blood flow to a part of the brain due to occlusion or rupture of an artery to the brain. "The associations of this locus with the expression of ZCCHC14 and DNA methylation suggest that together they contribute to the etiopathogenesis of stroke by altering the function of the regulatory elements of cell proliferation." (PMID 35741740, 2022).
infection (2 papers, 2024 to 2025). The state of being infected such as from the introduction of a foreign agent such as serum, vaccine, antigenic substance or organism. "ZCCHC14 has been shown to interact with TENT4 during infections caused by HBV, HCMV, and HAV." (PMID 39456919, 2024). "Accordingly, in vitro transcribed hsRNAs with a 30 nt 3′ poly(A) tail were transfected into wildtype, ZCCHC14-depleted (ZCCHC14-KO), or TENT4A/B-depleted (TENT4A/B-KO) Huh-7.5 cells, and this was followed by infection with the 18f-NLuc reporter virus for 72 h." (PMID 40431677, 2025). "TENT4 can directly target viral nucleic acids introduced into the host during infection by regulating viral RNA tailing with involvement of several ZCCHC family proteins, including ZCCHC14, ZCCHC7, and ZCCHC2, facilitating this TENT4-mediated activity." (PMID 39456919, 2024).
tumor (2 papers, 2021 to 2023). "After the expression of ZCCHC14 was weakened, tumour proliferation and invasion ability were significantly increased and the phosphorylation level of the P38 signalling pathway was also significantly elevated." (PMID 33345444, 2021). "We found that ZCCHC14 inhibits the P38 pathway in lung tumour cells including A549 and H1299 cells, thereby inhibiting the proliferation and invasion of tumour cells." (PMID 33345444, 2021). "In NSCLC patients, the low expression of ZCCHC14 in tumour tissues was significantly correlated with TNM stage, differentiation degree and adverse clinical outcome (P < .05)." (PMID 33345444, 2021). "We used MAPK‐P38 pathway inhibitor doramapimod (BIRB 796) to inhibit P38 signalling pathway activity and determined that the agent significantly disrupted the function of ZCCHC14 and hindered the proliferation and invasion of the tumour." (PMID 33345444, 2021). "The mechanism of abnormal expression of ZCCHC14 in tumour tissues is unclear." (PMID 33345444, 2021). "ZCCHC14 might be associated with the progress of tumour metastasis, such as brain metastasis, although the function of ZCCHC14 in tumour has not been researched." (PMID 33345444, 2021). "The survival analysis revealed that the survival time of patients without ZCCHC14 expression in tumour tissues (60 ± 5 m) was significantly shorter than that of patients with ZCCHC14 expression (82 ± 4 m) (P < .05)." (PMID 33345444, 2021). "Otherwise, the role of ZCCHC14 in tumour tissues has never been researched." (PMID 33345444, 2021).
adenocarcinoma (1 paper, 2021). A common cancer characterized by the presence of malignant glandular cells. "Expression of ZCCHC14 was normal in alveolar cells and low or absent in adenocarcinoma cells of NSCLC patients." (PMID 33345444, 2021).
cancer (1 paper, 2021). A tumor composed of atypical neoplastic, often pleomorphic cells that invade other tissues. "The introduction of the P38 inhibitor doramapimod further confirmed that ZCCHC14 regulates the biological function of cancer cells and phosphorylation of P38 through the P38 signalling pathway." (PMID 33345444, 2021). "Colony formation experiments showed that down‐regulation of ZCCHC14 significantly promoted the proliferation of cancer cells (P < .05)." (PMID 33345444, 2021). "The low expression of ZCCHC14 in cancer tissues was significantly correlated with poor versus good differentiation, TNM advanced stage (III + IV) and male gender (P < .05)." (PMID 33345444, 2021). "The p‐P38 expression in both groups was relatively low and did not significantly change, indicating that doramapimod inhibited the function of cancer cells transfected with ZCCHC14‐KO plasmids." (PMID 33345444, 2021). "Colony formation and transwell assays also showed that doramapimod inhibited the proliferation and invasion of cancer cells transfected with ZCCHC14‐KO plasmids." (PMID 33345444, 2021). "The results of transwell assays showed that the invasion ability of cancer cells was significantly increased after down‐regulating the expression of ZCCHC14 (P < .05)." (PMID 33345444, 2021). "The proliferation and invasion ability of cancer cells transfected with ZCCHC14 CRISPR/Ca9 KO plasmids was significantly enhanced (P < .05)." (PMID 33345444, 2021). "To study the function of ZCCHC14 in cancer cells, we conducted in vitro experiments." (PMID 33345444, 2021). "Abnormal expression of ZCCHC14 in cancer tissue also suggests that it may have a different impact on cancer." (PMID 33345444, 2021). "Further analysis demonstrated that the expression of ZCCHC14 in NSCLC was significantly correlated with cancer development factors and clinical prognosis, indicating that it might represent a new molecular change in NSCLC." (PMID 33345444, 2021).
ZCCHC14 also shares sentences with these, for which no sentence is quoted: alcohol addiction (1 paper); gastric cancer (1); microcephaly (1); migraine (1); oral cancer (1); schizophrenia (1); vesicoureteral reflux (1).